HSF1 (heat shock transcription factor 1)
Diseases named in the same sentence as HSF1 in open-access papers (continued):
Sharing a sentence is not in itself a finding about the gene and the disease.
Sepsis (4 papers, 2014 to 2023). Sepsis is defined as life-threatening organ dysfunction caused by a dysregulated host response to infection. "As an important transcription factor, heat shock factor 1 (HSF1) plays an endogenous anti-inflammation role in the body and can alleviate multiple organ dysfunction caused by sepsis, which contributes to an uncontrolled inflammatory response." (PMID 35720321, 2022). "It is evident that HSF1 decreases the production of inflammatory mediators to attenuate the inflammatory responses caused by LPS, and HSF1 exerts protective effects against brain dysfunction in sepsis." (PMID 36741074, 2023). "Furthermore, HSF-1 has been reported to prevent the overproduction of pro-inflammatory cytokines in conditions such as sepsis, potentially decreasing the inflammation-associated damage." (PMID 25053922, 2014). "Although the expression of HSF1 increased in the septic mouse model, we are still assured that the elevated HSF1 antagonizes the sepsis in the CLP model." (PMID 36741074, 2023). "The CLP sepsis model and sham model were established in hsf1+/+ mice and hsf1−/− mice, and the models were sentenced to death after 12 h." (PMID 36741074, 2023). "Our works showed that HSF1 plays an important role in sepsis-induced brain injury by regulating NLRP3." (PMID 36741074, 2023). "Collectively, the findings of the present study demonstrated that HSF1 not only inhibited the development of ALI in sepsis but also suppressed the NLRP3 inflammasome activation and IL-1β maturation." (PMID 35720321, 2022). "It is confirmed that pyroptosis could initiate sepsis, implying that HSF1 could alleviate sepsis-induced brain dysfunction by blocking the initiation event of sepsis by inhibiting pyroptosis." (PMID 36741074, 2023). "As the results showed, HSF1 obviously increased in the CLP sepsis model." (PMID 36741074, 2023). "Currently, only HSF1 has been reported in sepsis-related studies." (PMID 35720321, 2022). "In sepsis, whether HSF1 can participate in the activation of the NLRP3 inflammasome by regulating the expression of TRAF3 is still unclear." (PMID 35720321, 2022). "Sepsis, endotoxin tolerance, and heat shock all display downregulation of innate immunity, sharing a common immune suppressive effect, possibly through HS factor 1 (HSF1) mediated competitive inhibition of nuclear factor kappa-B (NF-κB) binding." (PMID 24524071, 2014). "However, whether HSF1 regulated NLRP3 in sepsis-induced brain injury, as well as the detailed mechanism of HSF1 in brain injury, remains unknown in the sepsis model." (PMID 36741074, 2023). "HSF1 could protect many organs such as the liver, lung, and kidney in the sepsis animal model." (PMID 36741074, 2023). "However, whether HSF1 affects the NLRP3 inflammasome activation during sepsis-induced ALI and its molecular mechanisms remains unknown." (PMID 35720321, 2022). "In this research, we try to explore the relationship between HSF1 and NLRP3 in a sepsis model and try to reveal the mechanism of HSF1 inhibiting the process of brain injury." (PMID 36741074, 2023). "However, whether HSF1 could alleviate brain injury in sepsis remains revealed." (PMID 36741074, 2023). "In order to demonstrate the protective effects of HSF1 against sepsis-induced lung injury, CLP was used to prepare the sepsis model, and the survival curve was plotted." (PMID 35720321, 2022). "HSF1 can protect the lung, liver, and kidney from multiorgan dysfunction syndrome induced by sepsis, but the function and expression in the brain had not been demonstrated." (PMID 36741074, 2023). "Moreover, HSF1 can regulate the innate immunity of the NLRP3 inflammasome, leading to the protection of sepsis." (PMID 36741074, 2023). "Because the exact mechanism of HSF1 in the process of sepsis still had not been demonstrated, the expression of inflammatory factors was further assessed in the hippocampal tissue of hsf1+/+ mice." (PMID 36741074, 2023).
acute lung injury (3 papers, 2020 to 2023). A condition of lung damage that is characterized by bilateral pulmonary infiltrates (pulmonary edema) rich in neutrophils, and in the absence of clinical heart failure. "Our recent research proved that HSF1 was involved in the activation of the NLRP3 inflammasome in septic acute lung injury (ALI)." (PMID 36741074, 2023). "However, whether HSF1 is involved in the activation of the NLRP3 inflammasome in septic acute lung injury (ALI) has not been reported." (PMID 35720321, 2022).
acute lymphoblastic leukemia (3 papers, 2019 to 2022). Leukemia with an acute onset, characterized by the presence of lymphoblasts in the bone marrow and the peripheral blood. "Indeed, a common regulator of HSF1 and a series of key HSP genes was recently described for T cell acute lymphoblastic leukemia (T-ALL) in the intercellular-signaling receptor NOTCH1." (PMID 32331382, 2020).
atherosclerosis (3 papers, 2023 to 2025). A disease characterized by the build-up of fatty material and calcium deposition in the arterial wall resulting in partial or complete occlusion of the arterial lumen. "Taken together, these data show that Pcnt-deficient SMCs have increased HSF1 activation, cholesterol biosynthesis, and cholesterol ester levels, along with augmented expression of some markers of atherosclerosis-associated phenotypic modulation." (PMID 37937642, 2023). "HSF1 has also been linked to atherosclerosis-related cardiovascular disorders, and evidence is mounting that HSF1 plays a crucial role in these conditions." (PMID 37077734, 2023). "Since activation of PERK may be downstream of progerin-induced cellular stress, SMC activation of HSF1/HMGCR/PERK may contribute to the increased risk for atherosclerosis in individuals with HGPS." (PMID 37937642, 2023). "For ACTA2 and PCNT pathogenic variants, SMC cytosolic stress that activates HSF1/HMGCR/PERK signaling contributes to early-onset atherosclerosis, raising the possibility that SMC cytosolic stress underlies premature atherosclerosis associated with other genetic diseases." (PMID 37937642, 2023). "For example, HSF1 phosphorylation at Ser326 activates HSF1 to upregulate HSPs expressions, which can protect against atherosclerosis." (PMID 37077734, 2023). "Nonetheless, the detailed mechanism for how HSF1 regulates atherosclerosis through mediating lipid homeostasis requires further investigated." (PMID 37077734, 2023). "Nevertheless, the evidence of HSF1 regulation in macrophage-foam cell in atherosclerosis is limited." (PMID 37077734, 2023). "Among multiple signaling pathways that regulate HSPs expression in atherosclerosis, the HSF1 pathway is a dominant mechanism in response to stresses." (PMID 37077734, 2023). "This review highlights roles of HSF1 and HSPs in critical metabolic pathways of atherosclerosis, including lipogenesis and proteome homeostasis." (PMID 37077734, 2023). "This review will focus on discussing influences that HSF1 and HSPs have on atherosclerosis and focus on macrophage foam cells due to space limitation." (PMID 37077734, 2023). "Finally, we infer that the mechanism of HSF1-mediated lipid metabolism may present novel therapeutic targets for cardiovascular disorders linked with atherosclerosis and that the activation of HSF1 and HSPs may serve as diagnostic indicators for atherosclerosis." (PMID 37077734, 2023). "A comprehensive understanding of the relationship between HSF1/HSPs and atherosclerosis is therefore essential for the development of effective treatment approaches or the identification of clinically useful markers for atherosclerosis." (PMID 37077734, 2023). "Limited data from a HGPS mouse model provide evidence that HSF1/HMGCR/PERK signaling may contribute to early atherosclerosis in patients with HGPS." (PMID 37937642, 2023). "HSF1 inhibition improves the lipidemic profile through enhancing cholesterol clearance and lowers atherosclerotic lesion load, making it a plausible target in atherosclerosis management." (PMID 37077734, 2023). "Furthermore, HSF1 deficiency increases the expression of cholesterol 7-hydroxylase (CYP7A1) and multidrug transporter (MDR1) genes, hence reducing atherosclerosis." (PMID 37077734, 2023). "It is possible that different HSF1 phosphorylations may have different effects on HSPs expressions and atherosclerosis." (PMID 37077734, 2023). "Heat shock factor 1 (HSF1) is involved in the control of atherosclerosis." (PMID 37077734, 2023). "HSF1 might be a nice marker in obesity-related disorders, including atherosclerosis." (PMID 37077734, 2023). "HSF1 phosphorylation therefore may play a role in atherosclerosis." (PMID 37077734, 2023).
atherosclerosis (continued). "Thus, MOPDII is the second Mendelian disorder that predisposes to early onset atherosclerosis by augmenting SMC cytosolic stress, activating downstream HSF1/HMGCR/PERK signaling, and increasing SMC migration and atherosclerosis-associated phenotypic modulation." (PMID 37937642, 2023). "This review discusses an intimate relationship between atherosclerosis and PSR, focusing on HSF1 and HSPs in atherosclerotic lipid homeostasis." (PMID 37077734, 2023). "The molecular mechanism uncovered by this study reinforces the critical contribution of SMCs in the pathogenesis of atherosclerosis and further emphasizes SMC cytosolic stress and HSF1 activation as a pathway driving atherosclerotic plaque formation independently of plasma cholesterol levels." (PMID 37937642, 2023). "Moreover, kinases and signaling pathways that regulate HSF1 phosphorylation in atherosclerosis have not been fully characterized." (PMID 37077734, 2023). "However, roles that HSF1 and HSPs play in the development of atherosclerosis are not completely known." (PMID 37077734, 2023).
Azoospermia (3 papers, 2020 to 2025). Absence of any measurable level of sperm,whereby spermatozoa cannot be observed even after centrifugation of the semen pellet. "Specifically, the HSF family members, HSF1 and HSF2, are likely to play important roles in human spermatogenesis as some azoospermia patients harbor deletion of HSFY on AZFb." (PMID 33318309, 2020).
cardiomyopathy (3 papers, 2016 to 2021). A disease of the heart muscle or myocardium proper. "Our results show that the elevation of the CHIP TPR domain and HSF1 effectively reverse DOX-induced cardiomyopathy." (PMID 27809308, 2016). "Administration of an HSF1 activator reversed DOX-induced cardiomyopathy." (PMID 27809308, 2016).
endometriosis (3 papers, 2021 to 2022). The growth of functional endometrial tissue in anatomic sites outside the uterine body. "HSF1 is a vital regulator of the heat shock response and has an essential role in developing endometriosis." (PMID 36339263, 2022). "Taken together, our study reveals the theoretical basis for the OTUB1/HSF1 axis as a potential target for the treatment of endometriosis." (PMID 36339263, 2022). "In this study, we demonstrate that OTUB1 promotes the development of endometriosis via deubiquitination of HSF1." (PMID 36339263, 2022). "Conversely, HSF1 knockdown inhibited the growth of endometriosis cells, and inhibited cell migration." (PMID 34107992, 2021). "In the previous experiment of the current study, we showed that HSF1 promotes glycolysis in endometriosis cell." (PMID 34107992, 2021). "To determine the functions of HSF1 in glycolysis, we overexpressed or knocked down HSF1 in endometriosis cells." (PMID 34107992, 2021). "Taken together, HSF1-specific inhibitor KRIBB11 plays a therapeutic role in the mouse model of endometriosis." (PMID 34107992, 2021). "Taken together, our findings provide some new insights into the functions of HSF1/PFKFB3 axis in endometriosis development, which is as a new target to treat endometriosis." (PMID 34107992, 2021). "We examined the functions of heat shock factor 1 (HSF1) in endometriosis development through cell count assay, cell-scratch assay and clone formation experiments." (PMID 34107992, 2021). "Our study demonstrates that HSF1 plays a crucial role in endometriosis development, which is consistent with previous studies." (PMID 34107992, 2021). "Moreover, the HSF1 expression was increased in endometriosis and promoted endometriosis development through the enhancement of glycolysis in endometriotic cells." (PMID 36612107, 2022). "In summary, OTUB1 promotes the development of endometriosis by up-regulating HSF1." (PMID 36339263, 2022). "Because endometriosis cells have similar characteristics of invasion and metastasis with tumor cells, and HSF1 is a carcinogen promoting tumor progression, so we speculate that HSF1 plays a similar role in the occurrence and development of endometriosis." (PMID 34107992, 2021). "Consistently, the HSF1 inhibitor KRIBB11 could abrogate endometriosis progression in vivo and in vitro." (PMID 34107992, 2021). "To determine whether HSF1 plays an important role in endometriosis, we manipulated HSF1 expression in endometriosis cells." (PMID 34107992, 2021). "Moreover, cell-scratch tests and clone formation experiments revealed that HSF1 overexpression promoted cell migration and growth in endometriosis cells." (PMID 34107992, 2021). "Our data demonstrated that HSF1 promoted endometriosis development." (PMID 34107992, 2021). "To test this hypothesis, we manipulated HSF1 expression in endometriosis cells, and used a constructed mouse model." (PMID 34107992, 2021). "Our study provides a new idea for the clinical treatment of endometriosis by targeting HSF1." (PMID 34107992, 2021). "Taken together, our results indicate that HSF1 promotes PFKFB3 expression in endometriosis cells." (PMID 34107992, 2021). "Our data show that HSF1 plays an important role in the development of endometriosis." (PMID 34107992, 2021). "We found that HSF1 overexpression significantly promoted cell proliferation in endometriosis cells." (PMID 34107992, 2021). "Taken together, HSF1 is a promising target for endometriosis." (PMID 34107992, 2021). "Interestingly, HSF1 enhanced glycolysis via up-regulating PFKFB3 expression in endometriosis cells, which was a key glycolysis enzyme." (PMID 34107992, 2021). "Our data demonstrated that HSF1 promoted endometriosis development via enhancing PFKFB3 expression." (PMID 34107992, 2021). "Findings indicate that HSF1 plays an important role in endometriosis development, which might become a new target for the treatment of endometriosis." (PMID 34107992, 2021).
endometriosis (continued). "Moreover, HSF1 plays an essential role in developing endometriosis." (PMID 36339263, 2022). "OTUB1/HSF1 axis may become a new therapeutic target for endometriosis." (PMID 36339263, 2022). "Furthermore, we used a HSF1 inhibitor-KRIBB11 to establish a mouse model of endometriosis." (PMID 34107992, 2021). "Moreover, HSF1 was previously reported to be overexpressed in endometriosis." (PMID 34107992, 2021). "Heat shock transcription factor 1 (HSF1) is a significant regulator of the proteotoxic stress response and plays an essential role in developing endometriosis." (PMID 36339263, 2022). "However, the mechanisms regulating HSF1 protein stability in endometriosis remain unclear." (PMID 36339263, 2022). "Our data show that HSF1 promotes endometriosis development, and enhances glycolysis via up-regulating PFKFB3 in endometriosis cells." (PMID 34107992, 2021). "Therefore, we hypothesized that HSF1 also regulated the endometriosis development." (PMID 34107992, 2021). "However, the roles of HSF1 in endometriosis are still largely unknown." (PMID 34107992, 2021). "In addition, HSF1 regulates glycolysis through the upregulation of PFKFB3 expression, which ultimately promotes the development of endometriosis." (PMID 36339263, 2022). "Subsequently, to determine whether HSF1 inhibitor KRIBB11 could suppress glucose metabolism, we cultured endometriosis cells with KRIBB11." (PMID 34107992, 2021). "In mice, we treat with HSF1 inhibitor KRIBB11, which could effectively inhibit endometriosis development." (PMID 34107992, 2021).
endotoxemia (3 papers, 2020 to 2023). "Furthermore, HSF1 reduced leukocyte infiltration into the lungs and decreased the production of several inflammatory mediators, thereby attenuating inflammatory responses and exhibiting a protective effect on endotoxemia caused by LPS." (PMID 33381262, 2020). "In this study, we provided multiple lines of evidence that HSF1 attenuated the release of inflammatory cytokines in endotoxemia mice by upregulating Atg10." (PMID 36598250, 2023). "Our previous work has shown that HSF1 improved survival in mice with endotoxemia by inhibiting the inflammatory response." (PMID 35720321, 2022). "Our previous work showed that HSF1 alleviated multiple organ damages by inhibiting the release of inflammatory factors and leukocyte infiltration into the tissue of endotoxemia mice." (PMID 33381262, 2020). "In previous studies, we prepared an endotoxemia model using HSF1−/− and HSF1+/+ mice." (PMID 33381262, 2020). "Thus, HSF1-induced protection from endotoxemia was largely Atg10 dependent." (PMID 36598250, 2023). "Targeting of HSF1-Atg10-autophagy might be an attractive strategy in endotoxemia therapeutics." (PMID 36598250, 2023). "In order to determine whether HSF1-mediated protective autophagy and protective effect are related to Atg10 in endotoxemia, cotransfection of pcDNA3.1-HSF1 with siRNA-ATG10 or siRNA-HSF1 with pcDNA3.1-ATG10 was performed in RAW264.7 cells." (PMID 36598250, 2023).
esophageal cancer (3 papers, 2015 to 2024). A primary or metastatic malignant neoplasm involving the esophagus. "For instance, it has been shown that HSF1 is frequently activated in CAFs from various tumor entities, including breast and esophageal cancers." (PMID 39243039, 2024).
female infertility (3 papers, 2011 to 2021). Diminished or absent ability of a female to achieve conception. "Female sterility caused by HSF1 deficit was found both in Drosophila and mice." (PMID 34198675, 2021). "Similarly, we observed reduced hsp90a expression in HSF1 KO medaka by RNA-seq analysis, indicating that this is also responsible for HSF1 KO female infertility." (PMID 31061435, 2019). "About vertebrates, mice lacking HSF1 possess multiple defects such as chorioallantoic placenta, prenatal lethality, growth retardation, female infertility and absence of the HSR; however, they can survive to adult age." (PMID 34198675, 2021). "Furthermore, mice lacking HSF1 can live to adulthood but have a severely compromised stress response and display several other defects including prenatal lethality, growth retardation and female infertility." (PMID 21264254, 2011).